CTNNB1 (catenin beta 1)
Diseases named in the same sentence as CTNNB1 in open-access papers (continued):
Sharing a sentence is not in itself a finding about the gene and the disease.
neurodevelopmental disorder (continued). "The patient had no definite ophthalmological symptoms, such as strabismus or vitreous retinopathy, but other phenotypes corresponded to CTNNB1-related neurodevelopmental disorders." (PMID 37416820, 2023). "We also provide an overview of the most recent research regarding CTNNB1 expression and its function in neurodevelopmental disorders." (PMID 37009120, 2023). "Autistic features have been reported frequently, shown in around 30% of patients with CTNNB1-related neurodevelopmental disorder." (PMID 35935366, 2022). "This study presented the genetic and clinical spectrum of CTNNB1-related neurodevelopmental disorder and identified some key clinical features of the disease." (PMID 35935366, 2022). "We reviewed a total of 69 patients with CTNNB1-related neurodevelopmental disorder reported in the literature, including our patients, and found that only one (1.4%) and three (5.4%) patients had seizure history and brain abnormalities, respectively." (PMID 35935366, 2022). "We enrolled 13 Korean patients with CTNNB1-related neurodevelopmental disorder who visited Seoul National University Children’s Hospital (5 female and 8 male patients with ages ranging from 4 to 22 years)." (PMID 35935366, 2022). "Such clinical features need to be investigated in more patients with CTNNB1-related neurodevelopmental disorder." (PMID 35935366, 2022). "This is one of the largest single-center cohorts of NEDSDV, expanding the clinical and genetic spectrum of CTNNB1-related neurodevelopmental disorders." (PMID 35935366, 2022). "In this study we summarized the clinical presentations of 13 NEDSDV or CTNNB1-related neurodevelopmental disorder patients in our center." (PMID 35935366, 2022). "A literature review revealed a female predominance of autistic features in CTNNB1-related neurodevelopmental disorder." (PMID 35935366, 2022). "Our manuscript may contribute to the better understanding of the genetic background of the recently discovered CTNNB1 neurodevelopmental disorder and raise awareness among clinicians and geneticists." (PMID 38225558, 2024). "CTNNB1 neurodevelopmental disorder shows autosomal dominant inheritance." (PMID 38225558, 2024). "Disruption of the interactions of the CTNNB1 protein with its ligands may lead to impaired synaptic plasticity, neuronal network connectivity, brain malformations, and consequently, to the development of the CTNNB1 neurodevelopmental disorder." (PMID 38225558, 2024). "This is one of the largest single-center cohorts of CTNNB1-related neurodevelopmental disorder." (PMID 35935366, 2022). "Therefore, we hypothesize that such a low frequency of seizure or brain abnormality might be rather a clinical characteristic of CTNNB1-related neurodevelopmental disorder." (PMID 35935366, 2022). "Among the 69 patients with CTNNB1-related neurodevelopmental disorder we reviewed, none of them had apparent seizure history or abnormal electroencephalogram results." (PMID 35935366, 2022). "A recent study also reported that no genotype-phenotype correlations have been identified in CTNNB1-related neurodevelopmental disorder to date." (PMID 35935366, 2022).
adenocarcinoma (18 papers, 2014 to 2025). A common cancer characterized by the presence of malignant glandular cells. "All patients had adenocarcinoma, and CTNNB1 mutations were detected at initial diagnosis, predominantly as subclonal alterations (73.3%, n = 11/15)." (PMID 40768678, 2025). "Some adenocarcinomas develop following the mutational activation of β-catenin (CTNNB1), regulated by APC, or through an alternative pathway involving the inactivation of tumor suppressor genes responsible for DNA repair." (PMID 40310348, 2025). "A single EGFR mutation was a good prognostic marker, but EGFR/CTNNB1 co-mutations showed a significantly shorter RFS even for stage I adenocarcinoma, most of which were cured." (PMID 33140254, 2021). "We report the first case of mesonephric adenocarcinoma of the cervix with lung metastases showing a CTNNB1 gene mutation." (PMID 31266530, 2019). "Most low-grade fetal adenocarcinoma/well-differentiated fetal adenocarcinoma (WDFA) of the lung shows nuclear expression of β-catenin and CTNNB1 somatic mutations, but the coexistence of mutations in CTNNB1 and DICER1 is uncommon." (PMID 40892116, 2025). "EBVaGCs with intestinal histology were frequently accompanied by genetic alterations, which were known to frequently occur in conventional intestinal-type adenocarcinoma, including KRAS, FBXW7, MUC6, ERBB2, CTNNB1, and ERBB2 amplification mutations." (PMID 37945587, 2023). "We identified frequent CNVs of the ATRX and RB1 genes in NENs and key driver mutations of the ARID1A, PIK3CA, CTNNB1, and MYC genes in nNENs, especially adenocarcinomas." (PMID 34422662, 2021). "A similar mechanism was recently described in H-1975 cells (a human adenocarcinoma cell line) where RA promotes the activity of GATA6, a transcriptional repressor, to down-regulate Ctnnb1 expression." (PMID 30568578, 2018).
benign tumor (7 papers, 2019 to 2026). "In summary, CTNNB1 mutations are associated with a unique melanocytic tumor type in benign tumors (nevi), which can be applied in a diagnostic setting." (PMID 36077603, 2022).
metabolic disease (7 papers, 2014 to 2025). A congenital disorder (due to inherited enzyme abnormality) or acquired (due to failure of a metabolically important organ) disorder resulting from an abnormal metabolic process. "Another study defined three other major HCC subtypes: mitogenic and stem cell-like tumors with chromosomal instability, CTNNB1-mutated tumors displaying immune suppression, and metabolic disease-associated tumors." (PMID 36428813, 2022). "GM dysbiosis and inflammation also induce epigenetic alterations in cytokine genes, such as IL-1β, IL-6, TNF-α, NF-kB, BTLA, IL-18R1, TGF-β, P13k/Akt1, Ctnnb1, and Hsp90aa1, as well as DNMTs, HDACs, and DAT1 associated with the development and progression of metabolic disorders and/or NPDs." (PMID 41228440, 2025). "Our latest integrated analysis of genome, transcriptome and clinicopathological data has revealed that the non-aggressive group is further divided into the catenin beta-1 (CTNNB1)-mutated subtype and the metabolic disease-associated subtype, the latter of which is mainly composed of non-viral HCC8." (PMID 37296228, 2023).
bacterial infection (4 papers, 2021 to 2024). "Moreover, the intracytoplasmic cell concentration of β-catenin (β-cat), a ligand of E-cad, was reduced after bacterial infection, suggesting that the bacterium induces modulation of the E-cad/β-cat signaling pathway and CDH1 and CTNNB1 genes transcription." (PMID 37285354, 2023).
colorectal (4 papers, 2015 to 2021). "Activation of the WNT/β-catenin (CTNNB1) signaling pathway plays a critical role in colorectal carcinogenesis." (PMID 32811441, 2020). "Thus, the eight gene panel (CXCL12, CK7, CDH1, CTNNB1, CD44v6, MUC16, TGFBR2 and HIF1A) can be a highly significant predictor of liver metastasis outcome independent of the standard prognostic criteria." (PMID 30383826, 2018).
neurological disease (4 papers, 2017 to 2025). "The study shows that proteins (SOX2, STAT1, AKT1, and CTNNB1) can be used as markers for neurological disease at the early stage of neuronal development, and they can be potential drug targets for therapeutic development." (PMID 30598663, 2018).
colon (3 papers, 2014 to 2018). "Indeed, CTNNB1 is an important oncogene in gastrointestinal tumors, and this gene is tightly regulated during normal liver development." (PMID 24798046, 2014).
psychiatric disorder (3 papers, 2020 to 2023). A disorder characterized by behavioral and/or psychological abnormalities, often accompanied by physical symptoms. "Finally, β-catenin encoded by CTNNB1 is implicated in a number of molecular pathways relevant in psychiatric disorders." (PMID 33193575, 2020).
cardiovascular diseases (2 papers, 2018 to 2021). "At least 6 critical genes, namely CTNNB1, HNRNPA1, SRSF4, TRA2A, SFPQ, and RBM5, and two large clusters of biological terms which are associated with the cardiovascular diseases are deregulated in the presence of omeprazole." (PMID 34659661, 2021).
gynecologic tumors (2 papers, 2024 to 2025). "Mutations in the CTNNB1 gene have an oncogenic effect and have been described in various solid tumors, including gynecological neoplasms." (PMID 39727978, 2024). "Notch receptor NOTCH2 and Wnt gene CTNNB1 expression were also significantly reduced in other gynecologic tumors when compared to benign tissues (FC = 1.32, and 1.62, respectively; p = 0.002)." (PMID 40002854, 2025).
kidney disease (2 papers, 2013 to 2022). "Like CCND1, CTNNB1 and ERBB2 are also involved in numerous cellular functions and kidney disease." (PMID 23637735, 2013).
head/neck tumors (1 paper, 2025). "Despite the larger number of patients in this combined analysis, the number of patients in some subgroups was still low, such as the number of patients with head/neck tumors and “other” CTNNB1 mutations." (PMID 39620931, 2025).
hematopoietic cancers (1 paper, 2025). "The CTNNB1 variant acts as a somatic reversion of the monogenic defect, giving CTNNB1-mutant cells a proliferative advantage, similar to mechanisms in some hematopoietic cancers." (PMID 40221090, 2025).
neurodegenerative disease (1 paper, 2024). A disorder of the central nervous system characterized by gradual and progressive loss of neural tissue and neurologic function. "SS + RSD mice show enrichment for genes related to neurodegenerative disease processes (CTNNB1, CSF1R, VCP), while sirtuins, which prevent aging and neurocognitive diseases, were less enriched." (PMID 39629138, 2024).
CTNNB1 also shares sentences with these, for which no sentence is quoted: papillary thyroid carcinoma (5 papers); acute myeloid leukemia (4); heart failure (4); squamous cell carcinoma (4); triple-negative breast carcinoma (4); CNS tumor (3); ductal carcinomas (3); genetic disorders (3); germ cell tumor (3); kidney cancer (3); alopecia (2); amyotrophic lateral sclerosis (2); Anxiety (2); Astigmatism (2); colorectal polyps (2); Crohn disease (2); diffuse large B-cell lymphoma (2); dilated cardiomyopathy (2); ductal adenocarcinoma (2); Dystonia (2); embryonal carcinoma (2); ependymoma (2); essential hypertension (2); Fanconi anemia (2); head and neck cancer (2); hyperaldosteronism (2); in situ breast cancer (2); inflammatory bowel disease (2); Kidney Clear Cell Carcinoma (2); Liver Disease (2).
A further 183 diseases each share a sentence with CTNNB1 in 2 papers or fewer.